ZNF792 (zinc finger protein 792)
Description:
May be involved in transcriptional regulation.
Synonyms: FLJ38451
Tractability: PROTAC: ubiquitination databases record sites on it.
Gene: Protein-coding gene on chromosome 19 (34,956,354 to 34,964,284, reverse strand). Ensembl gene ENSG00000180884.
Subcellular location: Nucleus
Subcellular location (Human Protein Atlas): Nuclear bodies; Nucleoplasm
Pathways (Reactome):
Gene expression (Transcription): Generic Transcription Pathway
Gene Ontology:
Molecular function: identical protein binding; protein binding; DNA-binding transcription factor activity, RNA polymerase II-specific; RNA polymerase II cis-regulatory region sequence-specific DNA binding
Biological process: regulation of transcription by RNA polymerase II; regulation of DNA-templated transcription
Cellular component: nucleus
Genetic constraint (gnomAD): Loss-of-function variants: 14 observed, 13.85 expected, observed/expected ratio (o/e) 1.01, 90% interval 0.67 to 1.57. The upper end of that interval is the gene's LOEUF score, 1.57, which puts it in group 6 of 6, group 1 being the genes least tolerant of losing a copy. Missense variants: 740 observed, 843.3 expected, observed/expected ratio (o/e) 0.88, 90% interval 0.82 to 0.93. Synonymous variants: 257 observed, 303.09 expected, observed/expected ratio (o/e) 0.85, 90% interval 0.76 to 0.94.
Homologues: Orthologues: chimpanzee ZNF792 (99% identical), macaque ZNF792 (95% identical), dog ZNF792 (75% identical), pig ZNF792 (74% identical), mouse Zfy1 (19% identical), tropical clawed frog zfx (19% identical), mouse Zfy2 (18% identical), rat Zfy1 (18% identical), zebrafish zfx (18% identical). Paralogues in human: ZNF551 (48% identical), ZNF304 (47% identical), ZNF256 (46% identical), ZNF548 (43% identical), ZNF549 (42% identical), ZNF418 (41% identical), ZNF587B (41% identical), ZIK1 (40% identical), ZNF772 (37% identical), ZNF773 (36% identical), ZNF583 (35% identical), ZNF419 (34% identical), and 26 more.
Diseases named in the same sentence as ZNF792 in open-access papers:
ZNF792 is named in the same sentence as 3 diseases in open-access papers, as found by Europe PMC text mining. Sharing a sentence is not in itself a finding about the gene and the disease. The quoted sentences say what the papers report.
Crohn disease (1 paper, 2024). A gastrointestinal disorder characterized by chronic inflammation involving all layers of the intestinal wall, noncaseating granulomas affecting the intestinal wall and regional lymph nodes, and transmural fibrosis. "Other novel CpG sites identified were previously associated with Crohn’s disease, inflammatory bowel disease, smoking, and age for NALCN (cg03185794) and ZNF792 (cg24678320)." (PMID 38571307, 2024).
herpes simplex infection (1 paper, 2021). "Our study identified DE TFs such as ZNF180, ZNF763, ZNF792, ZNF718, and ZNF461 associated with asthmatic ASM cells and enriched for the herpes simplex infection pathway." (PMID 34257337, 2021).
ZNF792 also shares sentences with these, for which no sentence is quoted: inflammatory bowel disease (1 paper).